HMOX1 (heme oxygenase 1)
Diseases named in the same sentence as HMOX1 in open-access papers (continued):
Sharing a sentence is not in itself a finding about the gene and the disease.
non-small cell lung carcinoma (41 papers, 2010 to 2025). A group of at least three distinct histological types of lung cancer, including non-small cell squamous cell carcinoma, adenocarcinoma, and large cell carcinoma. "This study investigated the regulatory mechanism underlying adaphostin induction of heme oxygenase 1 (HMOX1) which plays a significant role in modulation of drug-induced toxicity in the non-small cell lung cancer cell line model, NCI-H522." (PMID 20618971, 2010). "The first, miR-1254, a negative regulator of heme oxygenase-1 (HO-1), is able to induce apoptosis and inhibit cell cycle progression in non-small cell lung carcinoma (NSCLC) by a two-sided approach." (PMID 30824562, 2019). "Thus, hsa-miR-1304 was regarded as a suppressor of heme oxygenase-1 expression, inhibiting cell growth and survival in non-small cell lung cancer cells." (PMID 41431653, 2025). "Our recent data confirmed the proangiogenic effect of miR-378a (both strands) in non-small cell lung carcinoma (NSCLC) and pointed at its correlation with heme-degrading enzyme, heme oxygenase-1 (HO-1)." (PMID 26839547, 2015). "Although there are no studies showing the relationship between HMOX2 and cancer yet, HMOX1, a paralog of HMOX2, was known as a poor prognostic predictor and its over-expression may increase the metastatic potential of non-small cell lung cancer." (PMID 28009993, 2017).
depression (40 papers, 2020 to 2026). "Concurrently, SFN has been shown to improve anxiety and depression symptoms in mice by activating the Nrf2/ heme oxygenase-1 (HO-1) signaling pathway and inhibiting the hypothalamic–pituitary–adrenal (HPA) axis and stress response." (PMID 39703344, 2024). "The heme oxygenase-1 (HO-1)/CREB signaling pathway is involved not only in the development of depression-like behaviors that can be developed after an ischemic episode, but also in the transformation of astrocytes into a neurotoxic and inflammatory type cell." (PMID 37891922, 2023). "Magnolol, a natural phenolic compound derived from Magnolia officinalis, alleviates CUMS-induced depression by suppressing pro-inflammatory M1 microglial polarization and promoting anti-inflammatory M2 polarization through the Nrf2/heme oxygenase-1 (HO-1)/NLRP3 signaling pathway." (PMID 40936908, 2025).
brain injury (39 papers, 2013 to 2025). Acute and chronic (see also brain INJURIES, CHRONIC) injuries to the brain, including the cerebral hemispheres, CEREBELLUM, and brain STEM. "Heme-oxygenase-1 (HO-1), a major antioxidant, protects cells and tissues against the attack of oxidative products in the presence of brain injuries." (PMID 31330871, 2019). "In a previous study, we demonstrated that EB-WE administration improved ischemic brain injury induced by carotid artery occlusion in rats through the upregulation of NRF-2 (nuclear factor erythroid 2-related factor 2) and HO-1 (heme oxygenase-1) expression." (PMID 39860028, 2025). "Intraperitoneal administration of TA can upregulate Nrf2, which activates antioxidant enzymes, including heme oxygenase-1 (HO-1) and superoxide dismutase (SOD), in animal models of traumatic brain injury and nephrotoxicity." (PMID 36046027, 2022). "Heme oxygenase 1 (HO1), an anti‐oxidant enzyme, is significantly increased by IPC, and HO1 knockout could abolish IPC‐induced protective effects on ischemic brain injury, indicating its critical role in IPC." (PMID 34237192, 2021). "Moreover, it has been reported that HMOX-1 derived metabolites including CO activated the mitochondrial function of astrocytes via HIF-1α/estrogen-related receptor α (ERRα) circuit and therefore play an important role in the repair of neurovascular function after ischemic brain injury." (PMID 32408627, 2020).
liver diseases (36 papers, 2005 to 2025). "We then analyzed the possible association between HMOX1 and UGT1A1 genotypes with laboratory markers of liver disease, inflammation, or fibrogenesis." (PMID 34943103, 2021). "It is reported that quercetin can attenuate oxidative stress in alcohol-induced liver disease via heme oxygenase-1 restoration, decreased lipid oxidation, and diminished ROS generation." (PMID 30671125, 2018). "Heme oxygenase-1 (HO-1), an effective antioxidant and anti-inflammatory and antiapoptotic substance, has been used for the treatment of heart, lung, and liver diseases." (PMID 29682161, 2018). "This is consistent with accumulation of HMOX1 in liver tissues of 24M p21HBx/+ mice, suggesting the severe effect of liver injury in the later stage of liver disease." (PMID 27708241, 2016). "Nuclear factor erythroid 2-related factor 2 (Nrf2) is one of the important antioxidant stress-signaling pathways in vivo, and heme oxygenase-1 (HO-1) is the downstream target protein regulated by Nrf2, which plays an important role in the occurrence and development of liver diseases." (PMID 37367685, 2023). "KEGG and Reactome analysis suggested enrichment for pathways associated with liver disease, lipid metabolism, and antioxidants such as PPARalpha and HMOX1, although the pathways did not survive after multiple comparisons (FDR > 0.05)." (PMID 36274151, 2022). "Interestingly, it has been demonstrated that metformin protects primary rat hepatocytes against oxidative stress-induced apoptosis via the induction of heme-oxygenase-1 (HO-1) and inhibition of JNK activation, which suggests a potential therapeutic option for liver diseases associated with OxS." (PMID 33530432, 2021). "Differences were neither found in the inflammatory parameters among patients with different HMOX1/UGT1A1 variants, nor in the severity of liver disease." (PMID 34943103, 2021). "Nuclear factor erythroid 2-related factor 2 (Nrf2) regulates antioxidant machinery and expresses a variety of antioxidant genes, including heme oxygenase-1 (HO-1) and superoxide dismutase 2 (SOD2), which alleviate oxidative stress and inflammatory responses in liver diseases." (PMID 32992548, 2020). "A previous study has suggested that induction of HO‐1 (HMOX1), which is one of the most important antioxidant proteins among the downstream target genes of Nrf2, has a protective effect on the liver under the stress conditions found during various liver diseases." (PMID 34811857, 2021).
osteoporosis (36 papers, 2012 to 2026). A condition of reduced bone mass, with decreased cortical thickness and a decrease in the number and size of the trabeculae of cancellous bone (but normal chemical composition), resulting in increased fracture incidence. "The molecular basis of Cd-induced ferroptosis in pathogenesis of osteoporosis, emphasizing heme oxygenase-1 (HO-1)/bilirubin axis and zinc deficiency, is presented." (PMID 41751190, 2026). "This study shows that HMOX1 is low-expressed in osteoporosis, and this gene may promote osteoporosis development by reducing MSC’s osteogenic differentiation ability and regulating bone metabolism." (PMID 38650009, 2024). "In this study, the random forest model was used to screen out five key ferroptosis genes, including CP, HAMP, HMOX1, FLT3, and SLC2A3, and these 5 differentially expressed key ferroptosis genes were preliminarily verified in the osteoporosis model constructed." (PMID 38650009, 2024). "Importantly, the osteoporosis-related phenotype resulting from muscle Bmal1 knockout or aging was alleviated by nighttime time-restricted feeding (TRF), which reestablished a feeding-driven diurnal variation in Hmox1 expression within the muscle and reduced serum IL-1α levels." (PMID 42259765, 2026).
rheumatoid arthritis (35 papers, 2012 to 2025). A chronic, systemic autoimmune disorder characterized by inflammation in the synovial membranes and articular surfaces. "Furthermore, there is a clear association between the induction of heme oxygenase-1 and a reduction in the expression of the numerous inflammatory cytokines observed for rheumatoid arthritis." (PMID 38542266, 2024). "Polymorphisms in HMOX1 are associated with susceptibility to rheumatoid arthritis (RA) and the progression of joint damage in RA patients." (PMID 38392579, 2024). "Evidence suggests that miR-182 target heme oxygenase-1 (HO-1) upregulates RANKL-induced osteoclastogenesis in inflammatory episodes in rheumatoid arthritis (RA) patients." (PMID 39452495, 2024).
cardiac hypertrophy (34 papers, 2012 to 2026). "Taken together, deficiencies in the expression and activity of Hmox‐1 lead to cardiac hypertrophy and increased CO in adult zebrafish." (PMID 38509740, 2024). "Induction of HMOX1 has been associated with chronic viral myocarditis and cardiac hypertrophy in mice." (PMID 38509740, 2024). "Further, KMUP-1 has been attributed to its effects on reducing oxidative stress by upregulation of heme oxygenase-1 and its ability to attenuate cardiac hypertrophy in a rat model." (PMID 41194853, 2025). "A previous study indicated that inhibition of HMOX1 activity increases oxidative stress, aggravating cardiac hypertrophy." (PMID 38509740, 2024). "The authors suggest that Hmox1 induction in the lungs may supress myocardial hypertrophy in MCT induced PAH." (PMID 36388115, 2022). "We hypothesized that XJEK may prevent isoproterenol (ISO)-induced myocardial hypertrophy (MH) in mice by ameliorating oxidative stress (OS) through a mechanism that may be related to the nuclear factor erythroid 2-related factor 2 (Nrf2)/heme oxygenase-1(HO-1) pathways." (PMID 36045660, 2022). "We proved that ASIV could attenuate cardiac hypertrophy by improving left ventricular function and structure and showed that the expression of nuclear factor-erythroid 2-related factor 2 (Nrf2) and its downstream gene heme oxygenase-1 (HO-1) increased in the high-dose ASIV intervention group." (PMID 31285785, 2019). "Systemic overexpression of HMOX1 aggravates cardiac hypertrophy induced by pressure overload and fails to prevent arterial dysfunction upon injury in mice." (PMID 38509740, 2024). "Unlike other screened hub DEGs, Hmox1 has been more thoroughly investigated to further contribute to myocardial hypertrophy and myocardial injury through activation of ferroptosis." (PMID 38402404, 2024).
gastric cancer (34 papers, 2013 to 2026). A primary or metastatic malignant neoplasm involving the stomach. "It is suggested that inhibiting NEK2 to promote HMOX1 transcription through Keap1/Nrf2 was an important mechanism to affect ferroptosis in gastric cancer cells." (PMID 38503948, 2025). "Collectively, our findings demonstrate that securinine induces ferroptosis, suppresses EMT, and inhibits gastric cancer cell proliferation predominantly through activation of the HMOX1-dependent ferroptosis pathway." (PMID 41001039, 2025). "The results showed that inhibiting NEK2 expression increased HMOX1 mRNA and protein levels in gastric cancer cells, consistent with the results of RNA-seq, while CHAC1 levels did not change." (PMID 38503948, 2025). "In gastric cancer, low HMOX1 expression promotes gastric cancer cell apoptosis, inhibits proliferation and invasion, and correlates with increased overall survival in gastric cancer patients." (PMID 37144125, 2023). "In order to verify our conjecture, we used Kaplan-Meier Plotter database to explore the effects of high and low expression of HMOX1 gene on overall survival (OS) of patients with gastric cancer." (PMID 37144125, 2023). "IM is a key link in gastric precancerous lesions, so we have reason to suspect that HMOX1 also plays a key role in gastric cancer." (PMID 37144125, 2023). "The ATF4-modulated genes, xCT (a cystine/glutamate anti-transporter), tribbles-related protein 3 (TRB3), heme oxygenase 1 (HO-1), and phosphoenolpyruvate carboxykinase 2 (PCK2), were associated with a poorer prognosis for gastric cancer patients." (PMID 30380689, 2018). "Combined with the previous results, it was shown that inhibiting NEK2 could promote the expression of HMOX1 through Keap1/Nrf2, enhance the ferroptosis sensitivity of gastric cancer cells, and further affect the cell biological function." (PMID 38503948, 2025). "Mechanism studies have found that inhibiting NEK2 could promote the expression of HMOX1, a gene related to ferroptosis, and enhance the sensitivity of gastric cancer cells to ferroptosis by increasing HMOX1." (PMID 38503948, 2025). "We evaluated the transcription levels of the genes Nrf2, GCLM, NQO1, and HMOX1 as well as the protein expression levels of these genes in gastric cancer cells to determine whether Nrf2 is involved in the CEP-induced oxidative stress mechanism." (PMID 38086844, 2023). "Induction of the antioxidant defense enzyme, heme oxygenase-1 (HO-1) in human endothelial and gastric cancer cells, rat gastric epithelial cells (RGM-1), or the epithelium of small intestine is also involved in acid-independent gastrointestinal mucosal protection." (PMID 24846271, 2014). "Moreover, PPC suppressed gastric cancer by activating HMOX1-mediated ferroptosis." (PMID 39403590, 2024). "In this study, we investigated the role of HMOX1 gene silencing and the application of zinc protoporphyrin (ZnPP), a known HMOX1 inhibitor, in regulating ferroptosis, cell cycle progression, and epithelial-to-mesenchymal transition (EMT) in gastric cancer cells." (PMID 41001039, 2025). "The treatment of polysaccharides at a high dose of 9.6 g/kg could protect against the precancerous lesions of gastric cancer (PLGC) in rats by activating the Nrf2 pathway and its downstream antioxidant enzymes like heme oxygenase 1 (HO-1) and NAD(P)H: quinone oxidoreductase-1 (NQO-1)." (PMID 36160715, 2022).
periodontitis (32 papers, 2016 to 2026). An acute or chronic inflammatory process that affects the tissues that surround and support the teeth. "The expressions of heme oxygenase-1 (HO-1) and malondialdehyde in periodontal tissue were significantly higher in the periodontitis group than in the control group." (PMID 27854327, 2016). "Moreover, TXNRD1 has emerged as a promising prognostic marker for T2DM risk, particularly in familial forms of the disease, while GCLC (p < 0.01) and GCLM as well as HMOX1 (both p < 0.05) appear to play a role under specific clinical conditions of periodontitis accompanying T2DM." (PMID 41109135, 2025). "In addition, heme oxygenase-1 (HO-1), which plays a role in orthodontic tooth movement and inflammation in periodontitis models, might activate cellular defense mechanisms against oxidative stress." (PMID 33807391, 2021).
Arthritis (31 papers, 2012 to 2026). Inflammation of a joint. "Lyn deficiency exacerbates nephritis and arthritis in mice, while HMOX1 upregulates the expression of glomerular decay-accelerating factors and minimizes complement deposition and injury." (PMID 38912505, 2024). "This β‐sitosterol nanoformulation ameliorates complete adjuvant‐induced arthritis in rats through nuclear factor‐kappa B (NF‐кB) and heme oxygenase 1/nuclear factor erythroid 2‐related factor 2 (HO‐1/Nrf‐2) pathway." (PMID 39619995, 2024). "Heme oxygenase-1 (HO-1) expression in splenic CD4+ T cells isolated from A77 1726-treated arthritis mice were assessed by western blotting." (PMID 28193225, 2017). "Its anti-arthritis effect may be due to the induction of pERK, Nrf2 and heme oxygenase-1 (HO-1) expression, and inhibition of STAT3 activation." (PMID 35979373, 2022). "In another study, in a murine arthritis model, quercetin treatment reduced IL-1β and TNF-α release, and inhibited levels of pre-pro-endothelin 1 and cyclooxygenase 2 mRNA by inhibiting the activation of NF-κB and heme oxygenase 1/Nrf2 signaling." (PMID 34248976, 2021). "Although Hmox1 seems to alter macrophage activity, no involvement with arthritis is described in the literature." (PMID 24505471, 2014).
intracerebral hemorrhage (31 papers, 2004 to 2025). A cerebrovascular disorder characterized by bleeding into one or both cerebral hemispheres including the basal ganglia and the cerebral cortex. "The potential of heme oxygenase-1 (HO-1) as a biomarker and therapeutic target is also to be considered, as elevated serum levels of HO-1 have been associated with better outcomes in patients with intracerebral hemorrhage." (PMID 40227270, 2025). "Another study displayed that high HMOX1 expression promoted microglia survival in the intracerebral hemorrhage environment, further promoting inflammation and oxidative damage." (PMID 37529171, 2023). "The other cause is the heme and globin formed by erythrocyte lysis after intracerebral hemorrhage, after which heme is degraded into iron ion, bilirubin, and CO under the action of heme oxygenase-1 (HO-1)." (PMID 35481263, 2022). "Moreover, the heme scavenger hemopexin (HPX) can alleviate cognitive dysfunction in some studies related to intracerebral hemorrhage, and heme oxygenase-1 (HO-1), an enzyme that degrades heme, has neuroprotective effects." (PMID 38183122, 2024). "The chronicity of HO-1 action appears to be a crucial factor in determining outcome as HMOX1 in the GFAP.HMOX1 mouse model confers significant neuroprotection in the face of acute intracerebral hemorrhage." (PMID 39483365, 2022). "In addition, CR has been shown to reduce the neurological deficit in a heme oxygenase-1 (HO-1) knockout mouse model of intracerebral hemorrhage and reduce cytotoxicity induced by lethal agents." (PMID 35991882, 2022).
acute myeloid leukemia (30 papers, 2010 to 2025). Acute myeloid leukemia (AML) is a group of neoplasms arising from precursor cells committed to the myeloid cell-line differentiation. "HMOX1 has been also related to drug resistance in acute myeloid leukemia." (PMID 29559890, 2018). "Heme oxygenase-1 (HO-1) possesses antioxidative and antiapototic activity and may also contribute to the development of acquired chemoresistance in solid tumor tissue as well as acute myeloid leukemia cells." (PMID 27487134, 2016). "In acute myeloid leukemia, the PERK-NRF2 pathway activates heme oxygenase-1 (HO-1), an anti-inflammatory heme degradation enzyme, and suppresses the phosphorylation of p38." (PMID 41301006, 2025). "By contrast, in acute myeloid leukemia cells, BACH1 promotes cell death by inhibiting HMOX1 expression." (PMID 36670112, 2023).
cerebral malaria (30 papers, 2010 to 2026). A sequestration of Plasmodium falciparum in the brain, which can cause coma and/or seizures. "In particular, vulnerability to experimental cerebral malaria (ECM) was unearthed by the deletion of Hmox1 (the gene encoding HO-1) in otherwise resilient mice and was abrogated by HO-1 induction or carbon monoxide administration." (PMID 31417551, 2019). "Further research is needed to clarify how HMOX1 gene variants act in cerebral malaria pathogenesis but its tempting to speculate that genetic interaction with NOS2 functional variants may help to explain the contribution of HMOX1 to the genetic complexity of human cerebral malaria." (PMID 31417551, 2019). "Association results for cerebral malaria risk single-nucleotide polymorphisms (SNPs) genotyped in TGFB2, CD36, HBB and HMOX1 genes." (PMID 20585394, 2010). "Interestingly, it was demonstrated in the mouse that expression of Hmox1 induced by NO leads to protection from experimental cerebral malaria." (PMID 31417551, 2019). "Nrf2 activation induces HO-1 (heme oxygenase-1) expression and the production of CO, via haeme catabolism by HO-1, which acts ultimately as the gasotransmitter suppressing the onset of experimental cerebral malaria." (PMID 26551709, 2015). "Haplotypic quantitative trait analysis of HMOX1 gene expression in cerebral malaria patients." (PMID 20585394, 2010). "The Heme oxygenase-1 activity has been shown to suppress ECM in mice and one report in Myanmarese patients suggested that short alleles of a GT repeat in the HMOX1 promotor region are a risk factor for cerebral malaria." (PMID 20585394, 2010). "Furthermore, in a murine model of cerebral malaria and non-cerebral malaria, it has been demonstrated that Hmox1 deficiency exacerbates disease progression, resulting in host death irrespective of parasitemia." (PMID 39728801, 2024).